BEST2 (bestrophin 2)
Description:
Ligand-gated anion channel that allows the movement of anions across cell membranes when activated by calcium (Ca2+). Transports a large specter of anions, namely mediates the movement of chloride, L-glutamate and iodide. Calcium-binding triggers the dilation of the aperture, but calcium-dependent gating is only effective when the size of the passing anion is bigger than the closed aperture (By similarity). Mediates the calcium-activated hydrogencarbonate movement and participates in colonic hydrogencarbonate secretion concomitant with mucin secretion (By similarity). In non-pigmented epithelium (NPE), mediates the efflux of intracellular L-glutamate; binding of intracellular L-glutamate activates and open both the neck and the aperture of the channel, leading to L-glutamate exit promoting chloride influx movement from the extracellular side in trans. Also exhibits a directional permeability for intracellular glutamine, in a similar manner as for L-glutamate.
Synonyms: VMD2L1; FLJ20132
Tractability: Small molecule: a structure with a bound ligand is known. Antibody: UniProt places it where antibodies can reach, with high confidence; UniProt predicts a signal peptide or a membrane-spanning region; its Gene Ontology location is reachable by antibodies, with medium confidence.
Gene: Protein-coding gene on chromosome 19 (12,751,702 to 12,758,458, forward strand). Ensembl gene ENSG00000039987.
Subcellular location: Cell membrane; Basolateral cell membrane
Subcellular location (Human Protein Atlas): End piece; Flagellar centriole; Principal piece
Pathways (Reactome):
Transport of small molecules: Stimuli-sensing channels
Gene Ontology:
Molecular function: bicarbonate channel activity; chloride channel activity; intracellularly ligand-gated monoatomic ion channel activity; ligand-gated monoatomic cation channel activity; protein binding; ligand-gated monoatomic anion channel activity; channel activity
Biological process: chloride transmembrane transport; membrane depolarization; sensory perception of smell; bicarbonate transport; monoatomic cation transmembrane transport
Cellular component: basolateral plasma membrane; chloride channel complex; cilium; plasma membrane
Genetic constraint (gnomAD): Loss-of-function variants: 36 observed, 49.2 expected, observed/expected ratio (o/e) 0.73, 90% interval 0.56 to 0.97. The upper end of that interval is the gene's LOEUF score, 0.97, which puts it in group 4 of 6, group 1 being the genes least tolerant of losing a copy. Missense variants: 672 observed, 672.1 expected, observed/expected ratio (o/e) 1, 90% interval 0.94 to 1.07. Synonymous variants: 335 observed, 289.01 expected, observed/expected ratio (o/e) 1.16, 90% interval 1.06 to 1.27.
Homologues: Orthologues: chimpanzee BEST2 (99% identical), macaque BEST2 (99% identical), rat Best2 (90% identical), dog BEST2 (89% identical), mouse Best2 (89% identical), rabbit BEST2 (89% identical), pig BEST2 (87% identical), guinea pig BEST2 (86% identical), tropical clawed frog best2 (62% identical), zebrafish best2 (60% identical), Drosophila melanogaster Best1 (43% identical), Drosophila melanogaster Best4 (37% identical), and 18 more. Paralogues in human: BEST3 (52% identical), BEST4 (51% identical), BEST1 (50% identical).
Diseases named in the same sentence as BEST2 in open-access papers:
BEST2 is named in the same sentence as 10 diseases in open-access papers, as found by Europe PMC text mining. Sharing a sentence is not in itself a finding about the gene and the disease. The quoted sentences say what the papers report.
colitis (2 papers, 2013 to 2023). Inflammation of the colon. "Additionally, in the previous study, it was shown that BEST2-null mice spontaneously develop mild colitis." (PMID 24223998, 2013). "In addition, the study showed that the induction of colitis in those mice significantly exacerbated inflammation, delaying disease recovery and indicating that BEST2 may play a distinct role in both the initiation and the persistence of colitis." (PMID 24223998, 2013). "Additionally, as BEST2-knockout mice spontaneously develop colitis, it remains possible that BEST2 may play some role in the inflammation of UC, as suggested with other ion transporters, such as NHE1 and NHE3." (PMID 24223998, 2013).
glaucoma (2 papers, 2010 to 2021). Increased pressure in the eyeball due to obstruction of the outflow of aqueous humor. "On the other hand, Best2-specific inhibitors may provide utility in altering aqueous humor dynamics with the end goal of lowering intraocular pressure to treat glaucoma." (PMID 34612806, 2021). "This phenotype suggests that Best2 could be an attractive target for diminishing IOP in individuals with glaucoma." (PMID 20157619, 2010). "We conclude that Best2 represents a new potential target for glaucoma therapy." (PMID 20157619, 2010). "Consequently, these data support the hypothesis that modulation of Best2 activity may represent a new therapeutic avenue for lowering IOP in individuals with glaucoma." (PMID 20157619, 2010). "Mice lacking the BEST2 gene have altered aqueous humor flow and decreased intraocular pressure (IOP), suggesting Best2 may be a potential pharmaceutical target for lowering IOP (e.g., in the treatment of glaucoma)." (PMID 34612806, 2021).
ulcerative colitis (2 papers, 2013 to 2019). An inflammatory bowel disease involving the mucosal surface of the large intestine and rectum. "Such a lineage-specific expression was conserved in pathological conditions, as BEST2 expression was markedly down-regulated in active lesions of ulcerative colitis (UC) patients, in whom goblet cells are depleted." (PMID 24223998, 2013). "Significantly down regulation of BEST2 was found in the active lesions of ulcerative colitis." (PMID 31024853, 2019). "In addition, we found that BEST2 expression is significantly down-regulated in the active lesions of ulcerative colitis, where goblet cells were depleted, suggesting that BEST2 expression is restricted to goblet cells under both normal and pathologic conditions." (PMID 24223998, 2013).
asthma (1 paper, 2020). "GABA receptors, together with other factors, including GCR, bestrophin-2, and RAPL3, are common risk factors between moderate and severe asthma phenotypes." (PMID 32512817, 2020).
colon cancer (1 paper, 2023). "BEST2 is identified as one of the methylation markers for detecting the prognosis of colon cancer." (PMID 36928437, 2023).
cancer (2 papers, 2020 to 2022). A tumor composed of atypical neoplastic, often pleomorphic cells that invade other tissues. "Among them, 8 of 12 hub genes (EPHX3, SPINK7, FCRLA, MASP1, ZNF541, CD5, BEST2, ZAP70) seemed to be cancer-promoting genes as they were downregulated in the high-risk group." (PMID 35846149, 2022). "While some of these genes participate in basic cancer-related cellular functions such as proliferation and invasion, others, e.g., BEST2, play important roles in gut barrier function and anion transport." (PMID 31992345, 2020).
infection (2 papers, 2013 to 2025). The state of being infected such as from the introduction of a foreign agent such as serum, vaccine, antigenic substance or organism. "Furthermore, the bicarbonate ion channel Bestrophin-2 mRNA nominally increased, whereas the Cftr mRNA decreased during the late infection clearance phase." (PMID 24386378, 2013).
tumor (1 paper, 2022). "The findings revealed that ANO1, AQP9, and BEST2 were upregulated in tumor tissues, and AQP5, SCN4A, and SCNN1G expression was upregulated in normal tissue from 12 HNSCC patients." (PMID 36389709, 2022). "In the TCGA-HNSC cohort, we observed the expression of 12 ion channel genes in tumor and normal tissues; ANO1, AQP9, BEST2, CHRNA5, and KCNJ15 were upregulated in HNSCC, while AQP1, AQP5, SCNN1G, and SCN4A were downregulated." (PMID 36389709, 2022).
BEST2 also shares sentences with these, for which no sentence is quoted: head and neck cancer (1 paper); Macular dystrophy (1).